PAK1 (p21 (RAC1) activated kinase 1)
Diseases named in the same sentence as PAK1 in open-access papers (continued):
Sharing a sentence is not in itself a finding about the gene and the disease.
tumor (continued). "Interestingly, in this model, the tumor itself had an immunosuppressive effect, which was negated by PAK1 inactivation." (PMID 37830586, 2023). "Recent studies have shown that Ce6-PDT inhibits tumor cell migration by destroying the structure of actin cytoskeleton and reducing lamellipodium formation, which is closely related to the downregulation of Rac1/PAK1/LIMK1/cofilin." (PMID 37049739, 2023). "NMFH2 xenografts with ectopic PAK1 ovexpression and siCtrl exhibited larger average tumor volumes as per caliper measurement, which became significant from Day 10 post-implantation onward and kept this trend until Day 19, as compared with the group with empty vector and siCtrl (Figure-S8A)." (PMID 37564209, 2023). "Notably, PAK1 is also an upstream effector of STAT3 and NF-κB, associated with inflammation-associated malignancy, suggesting its role in inflammation-related tumor progression." (PMID 36012284, 2022). "It has been demonstrated that overexpression of PAK1 is able to induce malignant transformation of prostate epithelial cells, while the growth of tumor cells could be abrogated by blockade of PAK1 Ser223 phosphorylation." (PMID 36009534, 2022). "PAK1 was downregulated in NSCLC transplanted tumor tissues in vivo." (PMID 35500159, 2022). "The study of PAK1 in a PDAC mouse model demonstrate that the inhibition of PAK1 increases the tumor infiltration of CD4+ and CD8+ T cells, while reducing the intrinsic and PSC-induced PD-L1 expression in PDAC cells, which were then sensitized to cytotoxic lymphocytes." (PMID 36230657, 2022). "PAK1 was enhanced via miR‐615‐5p mimic but reduced via miR‐615‐5p downregulation in tumor cells." (PMID 35500159, 2022). "In GBM, LUSC, TGCT, BRCA, COAD, and THCA, PAK1 was positively correlated with the ICP gene expression, which suggested that PAK1 may regulated tumor immune response by immune checkpoint regulation." (PMID 36064705, 2022). "Because the abnormal activation of PAK1 in tumor tissues may promote tumorigenesis and development, this provides a direction for the development of PAK inhibitors." (PMID 36064705, 2022). "Besides, the suppressive role of hsa_circ_0004396 knockdown on cell migration and invasion in tumor cells was partially restored using miR‐615‐5p reduction or PAK1 elevation, as evidenced by decreased MMP‐2 level." (PMID 35500159, 2022). "Furthermore, the PAK1 inhibitor IPA‐3 exerted an anti‐tumour effect and its combination with ibrutinib exhibited a synergistic effect in ibrutinib‐sensitive and ‐resistant cells." (PMID 35811334, 2022). "However, due to the complexity and heterogeneity of the tumor microenvironment, as well as the crosstalk among oncogenic signaling pathways, the PAK1 mediated downstream molecular mechanism need deeply investigated." (PMID 34307365, 2021). "Thus, PAK1 appears to have a role in signaling from the stroma to the tumor, and from the tumor to the stroma." (PMID 34307365, 2021). "Fortunately, PAK1 can help the immune escape of tumor cells." (PMID 32863957, 2020). "Besides, regulation of cell cycle progression, apoptosis resistance, and immune escape; PAK1 also creates favorable conditions for the formation of tumor society." (PMID 32863957, 2020). "We performed immunohistochemical staining of 201 NSCLC resected tumor specimens for the TMA analysis to determine whether PAK1 expression was correlated with the clinicopathological characteristics of patients with NSCLC." (PMID 33261184, 2020). "Indeed, we have discovered here that both CBD and THC inhibited PC cell proliferation and xenografted tumour growth through a PAK1-mediated pathway as depletion of PAK1 by knockout reduced or blocked the inhibitory effects of these cannabinoids on PC." (PMID 33126623, 2020). "Thus, we adopted an experimental metastasis murine model that uses a tail‐vein injection method of tumor cells to specifically assess the effect of PAK1 silencing on the development of pulmonary metastasis in vivo." (PMID 31872963, 2020).
tumor (continued). "Furthermore, rescue experiments suggested that miR-26a/miR-26b exerted their tumor-suppression functions via targeting PAK1." (PMID 32190006, 2020). "Collectively, PAK1 activation contributes to the tumor society's stability and progress." (PMID 32863957, 2020). "PAK1 can stimulate the activation of hypoxia-inducible factors (HIFs) to promote the adaptation of tumor cells to hypoxic conditions and further induce metabolic reprogramming of tumor cells." (PMID 32863957, 2020). "Also, PAK1 enrichment was upregulated in TSCC tumor tissues and cell lines in contrast to corresponding negative controls, as expected." (PMID 32190006, 2020). "The contradictory results obtained with respect to the role of PAK1 in tumor migration determined from real-world data might be attributable to experimental limitations." (PMID 33261184, 2020). "PAK1 targeting is important for the management of bulk tumor cells and CSCs." (PMID 31658701, 2019). "Additionally, the tumor weights in the PAK1-knockout HAP1 cell-injected group were lower than those in the HAP1 control cell-injected group." (PMID 31658701, 2019). "Thus, PKCι-PAK1 signaling is an important pathway in tumor genesis in EGFR mutant, KRAS mutant and SCC cell lines." (PMID 31660987, 2019). "Collectively, these findings indicate that targeting PAK1 by pharmacological inhibitor IPA-3 could suppress tumor growth and metastatic behavior of ESCC cells and that it likely acts through blocking the Raf1/MEK1/ERK signaling pathway." (PMID 30971268, 2019). "Interestingly, we also found that pharmacological inhibition of PAK1 by IPA-3 significantly suppresses tumor growth and lung metastasis of ESCC cells in vivo and in vivo, suggesting PAK1 is promising therapeutic target for ESCC patients." (PMID 30971268, 2019). "Tumor volume of shRNA was smaller than that of NC on day 19, 23, 26, 27, and tumor weight of shRNA tended to be lighter than Blank and NC, and knockdown of PAK1 decreased DU145 PCa xenograft growth compared with the negative control." (PMID 28186966, 2017). "Furthermore inhibition of PAK1 by treatment of APC∆14/+ mice with PF-3758309 suppressed tumour growth in the colon and rectum and increased the numbers of neutrophils and lymphocytes in the blood." (PMID 28629331, 2017). "Inhibition of PAK1 seems to target the initial development of tumours more than their later growth." (PMID 28629331, 2017). "Indeed, qPCR analysis in oral squamous cell carcinomas (OSCC), revealed co-existing PIK3CA and PAK1 amplification in 37% of recurrent tumor samples." (PMID 27845911, 2017). "PSMA has been previously shown to be universally up-regulated on tumor-associated vascular endothelial cells in solid tumors and to participate in matrix degradation and facilitate integrin signaling and p21-activated kinase 1 (PAK-1) activation leading to productive tumor invasion." (PMID 27822700, 2017). "Levels of PAK1 remained low throughout tumour development in vivo." (PMID 28707321, 2017). "P21-activated kinase 1(PAK1) plays an important role in the regulation of cell morphogenesis, motility, mitosis, and angiogenesis and has been implicated with tumorigenesis and tumor progression." (PMID 26377044, 2015). "Interestingly, representative IHC images and quantification of IHC data of tumor tissues from the nude mice showed that sunitinib treatment increased p-PAK1, IL-6, CD73 and CD146 staining." (PMID 25675297, 2015). "Since knock down of either Pak1 or Pak2 slowed cell growth and tumor growth, we asked whether such inhibitory effects would be observed using Pak small-molecule inhibitors." (PMID 25596744, 2015). "Cytoplasmic PAK1 staining was strongly correlated with histological grade and the level of tumor cell proliferation, while positive nuclear PAK1 staining was correlated with tumor cell proliferation." (PMID 25182632, 2014).
tumor (continued). "In this study, we characterized PAK1 expression profiles to investigate its prognostic impacts and therapeutic implications using two cohorts of total 176 samples, and exploiting datasets of tumor samples and cell lines." (PMID 24236193, 2013). "After adjusting the prognostic factors which were established in univariate analysis, only PAK1 expression, pTNM stage, histological grade, tumor size, and sex maintained independent significance for overall survival (P<0.001, P = 0.045, P = 0.031, P<0.022 and P<0.010, respectively)." (PMID 24236193, 2013). "In addition, another regulatory molecule with tumor suppressive characteristics is miR-7, which targets a widely upregulated signaling kinase, p21-activated kinase 1 (Pak1)." (PMID 23202960, 2012). "Inhibition of PAK1 resulted in accumulation of cells in the G1 phase of the cell cycle, altered levels of E2F and p27Kip1 (which play multifaceted roles in regulation of G0 to S phase transitions of the cell cycle), and inhibition of in vivo tumor growth." (PMID 21653999, 2011). "We therefore hypothesized that PAK1 inhibition may synergize with other molecularly targeted agents to augment killing of tumor cells." (PMID 21653999, 2011). "Furthermore, PAK1 knockdown substantially decreased tumor cell proliferation (imaged by immunofluorescence staining of Ki-67 positive nuclei), migration and actin dynamics induced by hepatocyte growth factor (HGF) treatment." (PMID 21653999, 2011). "Similarly, the mean level of Pak1 protein expression in the tumor tissues was 2.68 (± 1.26), so a high expression group (49 patients) and a low expression group (59 patients) were separated by using this as the cut-off value." (PMID 20426825, 2010). "Primary tumors with LVI(+) and lymph node metastasis showed an increase of Rac1 activity and Pak1 expression, while metastatic lymph node tissues showed higher Rac1 activity and Pak1 expression than normal lymph nodes, indicating that Rac1 and Pak1 are involved in tumor metastasis." (PMID 20426825, 2010). "We investigated the correlation between Rac1 activity and Pak1 expression in tumor tissues." (PMID 20426825, 2010). "Pak1 overexpression is related to apoptosis-resistance in normal and tumour cells." (PMID 19497124, 2009). "Focal changes in copy number are thought to convey a selective advantage for tumor growth, so we next asked whether Pak1 is amplified in any of our cell lines." (PMID 19317917, 2009). "Furthermore, in transgenic mouse models, expression of activated Pak1 in breast epithelia is oncogenic, consistent with a functional role of Pak1 in tumor progression." (PMID 19557173, 2009). "Furthermore, PAK1 influences the expression of key molecules that facilitate tumor invasion, notably matrix metalloproteinases, which degrade extracellular matrix components to facilitate tumor cell dissemination." (PMID 41459112, 2026). "In this report, we found that Nischarin (NISCH), established as a tumor suppressor, is susceptible to S-glutathionylation, selectively at Cys185 located near its leucine-rich repeat (LRR) domains, which are implicated in protein-protein interactions with Rac1 and PAK1." (PMID 41213437, 2025). "Additionally, at the genetic level, PAK1 has been found to participate in tumor immunity." (PMID 40332759, 2025). "This suggested that PAK1 may have a role in tumor initiation." (PMID 40783411, 2025). "Ample data suggest that PAK1 may decrease cell sensitivity to programmed cell death, provide additional stimulation to growth-promoting molecular pathways, and contribute to the creation of an immunosuppressive tumor microenvironment." (PMID 37830586, 2023). "Thus, PAK1-inhibitors may be useful in ER positive tumours, to improve the effect of tamoxifen in these cases." (PMID 37368917, 2023).
tumor (continued). "Interestingly, it was noted that the inhibition of PAK1 also made NRAS-mutant cells more sensitive to the inhibitors of the MAPK cascade, suggesting an avenue to sensitize to targeted therapy this otherwise relatively resistant tumor variant." (PMID 37830586, 2023). "PAK1 confers TKI resistance to tumor cells, whether it is in EGFR-mutant or EGFR wild-type cells." (PMID 36230657, 2022). "Based on the increased migration and ECM attachment phenotypes, we postulated that PAK1 activation may play a crucial role in tumor progression when OS cells acquire abilities to attach on to endothelial cells, extravasate from the circulation, and migrate within the pulmonary parenchyma." (PMID 31872963, 2020). "Indeed, BCa patients with tumours that had nuclear PAK1 expression and phosphorylated ER S305, had significantly reduced responses to tamoxifen; nuclear expression of phosphorylated ER S305 was observed in 36% of patients and showed a trend towards reduced tamoxifen response." (PMID 32932819, 2020). "To test whether PAK1 silencing affects these metastatic processes, we conducted a time‐course study to follow the injected tumor cells at early time points (0, 3, 6, and 24 h after tumor cell injection)." (PMID 31872963, 2020). "However as less than 10% of tumours had both phosphorylated ER S305 and nuclear PAK1 expression, this suggests some redundancy and other kinases, such as PKA, may also be involved in the phosphorylation of ER S305." (PMID 32932819, 2020). "Therefore, PAK1 may promote tumor malignancy by activating Ras/Raf/MARK and β-catenin/TCF4 signaling." (PMID 27713506, 2016). "No such association was detected for time to tumor progression (HR = 1.78, 95% CI = 0.99-3.21).Our meta-analysis thus indicates that PAK1 expression may be a predictive marker of overall survival and disease-specific survival in patients with solid tumors." (PMID 27027431, 2016). "Finally, we provide evidence that PRL-induced pTyr-PAK1 stimulates tumor cell metastasis in vivo." (PMID 27542844, 2016). "Our results provide additional rationale for combination mTOR/MEK inhibitor therapy because in addition to the anti-proliferative effects of MEK inhibitor treatment, mTOR inhibition resulting in enhanced PAK1/JNK/FOXO3-mediated apoptosis could inhibit tumor progression." (PMID 26121028, 2015). "Knockdown of PAK1 could significantly suppress in vitro and in vivo tumor cell growth." (PMID 25093037, 2014). "In addition, high expression was associated with large tumor size (>6 cm vs. ≤6 cm, P = 0.006) and positive residual surgical margin (P = 0.033), while PAK1 levels were not remarkably altered between tumors of different histological grades." (PMID 24236193, 2013). "Together, these findings highlight the distinct mechanisms by which PAK1 and PAK4 regulate tumour growth, vasculature, and hypoxia." (PMID 41294859, 2025). "In tumor cell migration, CIB1 enhances tumor cell migration and adhesion by interacting with various molecules such as PAK1 and FAK, thereby promoting tumor invasion and metastasis." (PMID 40076845, 2025). "This study aims to investigate the effects of PAK1 and PAK4 on tumour vasculature, immune cell infiltration, and the connection between using PAK1-knockout (KO), PAK4 KO, and wild-type (WT) PDA cells in cell-based and mouse experiments." (PMID 40943273, 2025). "Despite evidence linking PAK signalling to immune regulation and vascular dynamics, the effects of PAK1 and PAK4 on tumour vasculature and chemotherapy response in PDA remain poorly defined." (PMID 41228228, 2025). "Preclinical studies have demonstrated that PAK selective inhibitors for PAK1 (FRAX597) and PAK4 (PF-3758309) suppress tumour growth and improve chemotherapy response across multiple solid tumours." (PMID 41228228, 2025). "Our data provides a comprehensive comparison of DepMap dependency scores for PAK1, PAK2, PAK3, PAK4, PAK5, and PAK6, based on CRISPR analysis of 1100 tumor cell lines and RNAi analysis of 711 cell lines." (PMID 39756822, 2025).
tumor (continued). "PAK1&4KO maintained the vascular normalisation of PAK1KO, but didn’t inhibit angiogenesis, contributing to the insignificant reduction in tumour weight." (PMID 41228228, 2025). "This study investigated the effects of PAK1 and PAK4 on tumour vasculature and therapeutic response in an immunocompromised mouse model." (PMID 41228228, 2025). "Inhibiting PAK1 not only diminishes PSC activation and increases tumor-infiltrating lymphocytes (TILs) but also enhances lymphocyte-induced tumor cell death." (PMID 40332759, 2025). "In this study, we used immunocompromised mice models to investigate how knockout PAK1 and/or PAK4 change the structure and function of tumour blood vessels and how these changes affect chemotherapy outcomes." (PMID 41228228, 2025). "We have explored the effects of PAK1 and PAK4 on the tumour vasculature of PDA and its impact on the PAK-regulated tumour immune response in this study." (PMID 40943273, 2025). "While the immunomodulatory roles of PAK1 and PAK4 in PDA have been investigated, the impact of PAK on tumour vasculature and how these vascular changes influence the immune system, including T-cells and dendritic cells, remains poorly understood." (PMID 40943273, 2025). "PAK1 is involved in the PI3K/AKT/mTOR pathway, contributing to tumor growth by activating β-catenin." (PMID 40699726, 2025). "Together, these results suggested that PAK1 and PAK4 differentially affected angiogenesis and tumour vasculature, leading to a differential impact on the effect of gemcitabine in this immunocompromised SCID mouse model." (PMID 41228228, 2025). "Recent studies have shown that IVM can exert anti-tumor effects through multiple pathways, such as inhibiting the WNT-TCF signaling pathway, modulating PAK1, and inducing mitochondrial dysfunction." (PMID 40699802, 2025). "Our findings highlight the distinct roles of PAK1 and PAK4 in modulating the tumour vasculature and immune microenvironment in PDA." (PMID 40943273, 2025). "Given the established involvement of PAK signalling in angiogenesis and immune regulation, we have further determined the effects of PAK1 and PAK4 on tumour vasculature in PDA, and their impact on therapeutic outcomes." (PMID 41228228, 2025). "Our recent work in immunocompetent syngeneic mouse model has shown that PAK1 or PAK4 knockout enhances vascular normalisation and anti-tumour immunity." (PMID 41228228, 2025). "The proteomic data further confirmed the differential roles of PAK1 and PAK4 in regulating tumour vasculature." (PMID 41228228, 2025). "We have recently reported that knockout of PAK1 or PAK4 enhanced vascular normalisation, stimulating anti-tumour immunity against PC in an immunocompetent syngeneic mouse model." (PMID 41228228, 2025). "In order to validate Pak1 as a marker of acquired mechanisms of resistance also in patients’ cohort, the evaluation of PAK1 expression might be investigated in future studies in tumor biopsies of patients with disease progression after ER+ plus CDK4/6i therapy." (PMID 37258566, 2023). "The acetylation of the hypoxia‐induced autophagy regulator PAK1 regulates the phosphorylation of ATG5 at Thr101 in GBM and is important for hypoxia‐induced autophagy and tumor growth." (PMID 37143582, 2023). "Conversely, over-expression of PAK1 in MCF7 and T47D cells increased tumor spheroids’ growth and invasion and reduced sensitivity to fulvestrant and abemaciclib, confirming its role in inducing drug resistance." (PMID 37258566, 2023). "PAK1 influences the production of VEGF, a growth factor that supports tumour invasion and metastasis." (PMID 38067120, 2023). "Both the GEFT and DEP domains containing 1B (DEPDC1B) can interact with Rac1 to activate Rac1 and downstream PAK1, thus promoting EMT and enhancing the invasion and migration of tumor cells." (PMID 37049739, 2023). "It was found that miR-331-3p inhibits Rac1/PAK1/β-catenin by targeting Vav2, thereby inhibiting EMT and the subsequent invasion and migration of tumor cells." (PMID 37049739, 2023).